LINC00184 (long independently transcribed non-coding RNA 184)
Synonyms: HANC; lnc-beta-Catm; NCRNA00184
Gene: Long non-coding RNA gene on chromosome 1 (234,609,295 to 234,637,418, forward strand). Ensembl gene ENSG00000224939.
Diseases named in the same sentence as LINC00184 in open-access papers:
LINC00184 is named in the same sentence as 8 diseases in open-access papers, as found by Europe PMC text mining. Sharing a sentence is not in itself a finding about the gene and the disease. The quoted sentences say what the papers report.
breast carcinoma (1 paper, 2019). "In summary, we have identified five novel lncRNAs (AL117190.1, COL4A2‐AS1, LINC00184, MEG3 and MIR22HG) related to prognosis of breast cancer, which could act as underlying prognosis biomarkers for breast cancer." (PMID 31613058, 2019). "Through survival analysis, 5 lncRNAs (AL117190.1, COL4A2‐AS1, LINC00184, MEG3 and MIR22HG) were identified as crucial prognostic factors for patients with breast cancer." (PMID 31613058, 2019). "From this analysis, we conclude that AL117190.1, COL4A2‐AS1, LINC00184, MEG3 and MIR22HG act as prognostic biomarkers, whose low expression revealed that patients with breast cancer have better overall survival." (PMID 31613058, 2019). "Notably, beginning with TCGA RNA transcript profiles collected from breast cancer specimens, via WGCNA and ceRNA bioinformatics analysis, we identified six lncRNAs, of which three (AL117190.1, COL4A2‐AS1 and LINC00184) are unknown." (PMID 31613058, 2019).
esophageal cancer (1 paper, 2021). A primary or metastatic malignant neoplasm involving the esophagus. "They found that highly expressed LINC00184 increases esophageal cancer cell proliferation, migration, invasion and colony formation." (PMID 33652661, 2021).
oesophageal cancer (1 paper, 2021). "However, LINC00184 was reported to be highly expressed in oesophageal cancer and regulate glycolysis and mitochondrial oxidative phosphorylation." (PMID 34651416, 2021). "The mechanism of action of LINC00184 in tumours is scarcely reported, except in oesophageal cancer." (PMID 34651416, 2021).
cancer (1 paper, 2021). A tumor composed of atypical neoplastic, often pleomorphic cells that invade other tissues. "Therefore, the role of LINC00184 in cancer should be the focus of future research." (PMID 34651416, 2021).
tumour (1 paper, 2021). "Furthermore, LINC00184 expression levels in NSCLC tumour tissues was notably associated with T classification, N classification and clinical stage." (PMID 34651416, 2021). "The 98 cases of NSCLC tumour tissues were grouped into high and low LINC00184 expression groups according to the LINC00184 median expression level." (PMID 34651416, 2021). "In the current study, we confirmed that LINC00184 was up‐regulated in NSCLC tumour tissues and cell lines and its high expression in NSCLC tissues indicated a poor prognosis for NSCLC patients." (PMID 34651416, 2021). "Results showed that LINC00184 was considerably overexpressed in NSCLC tumour cell lines when compared to that in the 16HBE cell line (P < 0.05 or P < 0.01)." (PMID 34651416, 2021). "The relative LINC00184 expression levels in the tumour group were significantly higher than those in the normal group (P < 0.0001)." (PMID 34651416, 2021). "We found that lncRNA LINC00184 was highly expressed in LC tumour tissues based on The Cancer Genome Atlas (TCGA) database." (PMID 34651416, 2021). "In the present study, we observed LINC00184 up‐regulation in NSCLC tumours, which was correlated with poor prognosis." (PMID 34651416, 2021). "LINC00184 suppressed tumour growth and proliferation in NSCLC mouse models and directly targeted the miR‐524‐5p/HMGB2 axis." (PMID 34651416, 2021). "A total of 98 pairs of NSCLC tumour tissues and non‐tumour tissues were collected and the expression levels of LINC00184 were detected via qRT‐PCR." (PMID 34651416, 2021). "LINC00184 expression in tumour tissues was positively correlated with the clinical stages of NSCLC." (PMID 34651416, 2021). "Nevertheless, the functional role of LINC00184 in tumours requires clarification." (PMID 34651416, 2021). "LINC00184 knockdown significantly inhibited tumour volume, weight and growth in vivo (P < 0.01)." (PMID 34651416, 2021). "At present, there are few studies on the role of LINC00184 in tumours." (PMID 34651416, 2021). "Additionally, we confirmed that LINC00184 knockdown repressed tumour growth and proliferation in vivo." (PMID 34651416, 2021). "Additionally, the expression level of LINC00184 in NSCLC tumour tissues was negatively correlated with miR‐524‐5p expression." (PMID 34651416, 2021). "Finally, we showed that LINC00184 knockdown could inhibit tumour growth and proliferation in vivo." (PMID 34651416, 2021). "We downloaded LINC00184 expression level data in 348 cases of NSCLC tumour tissues and 46 cases of adjacent normal tissues from TCGA database; results showed that LINC00184 was significantly overexpressed in NSCLC tumour tissues compared to that in normal tissues (P < 0.01)." (PMID 34651416, 2021).
LINC00184 also shares sentences with these, for which no sentence is quoted: gastric cancer (1 paper); non-small cell lung carcinoma (1); prostate carcinoma (1).